SPI1 (Spi-1 proto-oncogene)
Diseases named in the same sentence as SPI1 in open-access papers (continued):
Sharing a sentence is not in itself a finding about the gene and the disease.
infection (continued). "The objective of this study was to determine the prevalence of Salmonella serovars associated with human infections in Saudi Arabia using the rapid CTS system and to determine if the isolates contain SPI-1 and SPI-2 as well as characterizing the associated antimicrobial resistance." (PMID 31214517, 2019). "During the process of infection, Salmonella uses two molecular injectisomes known as Type 3 Secretion Systems (T3SS) to secrete virulence factors that are encoded by Salmonella Pathogenicity Island-1 (SPI-1) and SPI-2 into host cells." (PMID 31214517, 2019). "Moreover, Salmonella pathogenicity island 1 (SPI-1), which is required for virulence during the intestinal phase of infection, was induced by culturing S. Typhimurium to the stationary phase in Lysogeny Broth (LB)." (PMID 30214435, 2018). "Salmonella express two different T3SS translocons required for infection; T3SS-1, encoded by Salmonella Pathogenicity Island 1 (SPI-1) along with a subset of effector proteins, and T3SS-2, encoded by Salmonella Pathogenicity Island 2 (SPI-2) along with another cohort of effector proteins." (PMID 28848721, 2017). "Therefore, while the effectors encoded on SPI-1 and SPI-2 play roles in initial invasion and persistence, respectively, some of these same effectors from SPI-1, such as SipA, are also expressed during the more persistent phase of infection (7, –, 9)." (PMID 28630067, 2017). "In addition, mutants ΔinvA and ΔssaD were internalized in higher numbers than the wild-type strain during competitive infections, suggesting that S. Typhimurium requires the T3SS encoded in SPI-1 and SPI-2 to evade phagocytosis by D. discoideum." (PMID 27602025, 2016). "Using infection-relevant growth conditions, we identified a total of 1257 coding genes that are controlled by one or more regulatory system, including a sub-class of genes that reflect a new level of cross-talk between SPI1 and SPI2." (PMID 27564394, 2016). "In this study we therefore first characterized the response of chicken macrophage cell line HD11 to infection with wild-type S. Enteritidis and aroA, phoP, SPI1 and SPI2 mutants, as macrophages are considered to play a key role in the immune response to Salmonella infection." (PMID 26380970, 2015). "A significant time-dependent increase in Cxcl2 and Cxcl5 mRNA expression was measured after infection by WT or the complemented ΔinvC pinvC but not SPI1-deficient non-invasive Salmonella." (PMID 25210785, 2014). "In addition to the previous work, we identified multiple SPI-1 genes that are differentially expressed both in cultures and at several time-points post-infection of an in vitro challenge using human HCT-8 cells." (PMID 23442379, 2013). "However, like the early transcriptional responses, stimulation of the responses later in infection was also strictly dependent on the SPI-1 T3SS." (PMID 24098123, 2013). "However, even in the case of MMP7, its induction 4 days post-infection with the SPI1 mutant (35 fold) was significantly lower than after infection with wild-type Salmonella Enteritidis (1578 fold)." (PMID 23687968, 2013). "Similarly to non-opsonized Salmonella GPA, time-points of 1, 2.5, 4, and 6 h post-infection were chosen for testing of SPI-1 gene expression by qPCR." (PMID 23442379, 2013). "However, the fold induction (35 fold) after infection with the SPI1 mutant was 45× lower when compared with the MMP7 induction in the cecum of chickens infected with the wild-type Salmonella Enteritidis (1578 fold)." (PMID 23687968, 2013). "SPI-1 genes were found to be up-regulated over the wild-type as early as 1 h post-infection." (PMID 23442379, 2013). "The bacteria were grown to late log phase to ensure the expression of SPI-1 genes, so that both the invasive and the phagocytic mechanisms of infection could occur." (PMID 22552918, 2012). "Together, our results suggest that SPI-1 genes could represent S. Typhi virulence factors participating in optimal infection of human macrophages." (PMID 22574205, 2012).
infection (continued). "Since expression of the SPI1-T3SS and translocation of the SPI1-effector SipC is triggering host cell pyroptosis in phagocytic cells, the infection experiments were performed in an invC strain background that is non-invasive and unable to translocate SPI1 effector proteins." (PMID 22427996, 2012). "Tagging of the SPI-1 ORFs in these mutants did not impair the invasiveness, growth, or the virulence of the bacteria, and the tagged strains can be used as model strains to study the infection of Salmonella in vitro and in vivo, including the expression of SPI-1 proteins and effectors." (PMID 21949647, 2011). "Our proteomic results on SPI-1 proteins SipA, SipC, and SopB suggest that the expression of these proteins may be differentially modulated during infection under biologically relevant environments that resemble the oxidative stress condition." (PMID 20529336, 2010). "Thus, examination of the expression of SipC and other SPI-1 factors both in vitro and in vivo in the context of infection, as reported in our study, is crucial to ultimately understand the actual functions and actions of these factors." (PMID 20529336, 2010). "However, by 5 hr post infection, the levels of the three SPI-1 proteins diverged, with the SipC level increased, the SopB level decreased while SipA level remained unchanged." (PMID 20529336, 2010). "Furthermore, these results are also consistent with the observation that SPI-1 TTSS effector proteins are required for the induction of intestinal inflammation in animal models of infection." (PMID 19662166, 2009). "Furthermore, SPI-1 proteins, SipA, SopA, SopB, SopD, and SopE2 were found to be expressed by Salmonella in infected animals at the late stages of infection." (PMID 19371445, 2009). "SPI-1 mutants colonize the cecal contents of 1-week old Rhode Island Red chicks normally at one day post infection but have reduced colonization of cecal contents over the longer term at 3,7, and 14 days post infection." (PMID 18922185, 2008). "Concomitantly, SPI1-deficient mutants show a 10-fold reduction of LD50 in mice when given orally, whereas such mutants retain virulence via the intraperitoneal route, illustrating the importance of SPI1 in the early stages of infection, such as the invasion process." (PMID 18031307, 2008). "To determine whether the increased transcript levels of the SPI-1 apparatus corresponded to a functional PrgH that led to enhanced secretion of SPI-1 effectors during infection, we quantified the abundance of SipC—a SPI-1 effector—within 30 minutes of infecting Caco-2 cells." (PMID 40906700, 2025). "The increased infection levels at the earliest timepoint may reflect the upregulation of SPI-1." (PMID 39591989, 2024). "However, the contribution and related signaling pathways of SPI-1 and SPI-2 in inflammation caused by S. Enteritidis during the course of infection remain unclear." (PMID 37325511, 2023). "Therefore, an infection model with SPI-1-induced bacteria was tested." (PMID 35166652, 2022). "Taken together, these results show that hilD_a encodes for a non-functional regulator as observed in broth culture conditions and demonstrate that the absence of a functional HilD causes the lack of activation of SPI-1 expression over time during human cell infection." (PMID 33299016, 2020). "Although SPI-1 and SPI-2 are the most important PAIs associated to Salmonella pathogenicity, our results contribute to a growing amount of data suggesting that other genomic islands can regulate the progression of infection and even the expression of genes in SPI-1 and SPI-2." (PMID 31800631, 2019). "As infection progressed, we detected a robust upregulation of genes encoding cytokines and chemokines (CCL2, CCL3, IL1B, CXCR1, IL1RN) as well as granulocyte associated transcripts (TLRs 1-4, SPI1, S100A8, S100A9, CD177), which correlated with the higher numbers of granulocytes 5 DPI." (PMID 28852031, 2017).
infection (continued). "Relevant genes required for this process are located in pathogenicity islands such as SPI-1 and SPI-2, which encode two independent type III secretion systems (T3SSSPI-1 and T3SSSPI-2, respectively) that inject effector proteins into host cells and are critical during various stages of infection." (PMID 27602025, 2016). "However, during a mouse infection, S. typhimurium down regulates SPI-1 expression." (PMID 25879288, 2015). "However, some Salmonella lacking the T3SS-1 remain pathogenic in different in vivo infection models such as a SPI-1 mutant of S. Gallinarum in adult chicken or S. Typhimurium and S. Enteritidis mutants in one week-old chicks or Balb/C mice." (PMID 25653644, 2014). "Boolean modeling of the cross-talk network and subsequent simulation could reproduce the experimentally observed sequential activation of SPI-1, SPI-2 and T6SS, indicating that, the model could efficiently capture the underlying regulatory mechanism driving the progression of infection in vivo." (PMID 24079299, 2013). "Therefore, as differentiated THP-1 are phagocytic-type cells and infection is largely established via SPI2-encoded T3SS, low SPI-1 expression of invaded macrophages could therefore be expected based on previous efforts." (PMID 23442379, 2013). "Thus, Salmonella populations might be expected to behave heterogeneously during infection of host cells due to differential expression of SPI-1 and its effectors." (PMID 21493681, 2011). "Furthermore, these naturally occurring SPI-1 deficient strains invaded human monolayer cells less efficiently than laboratory constructed SPI-1 mutants, further demonstrating differences between monolayer systems and in vivo outcomes of infection." (PMID 21206750, 2010). "Furthermore, the ability of S. Typhimurium to induce inflammation in these animals also required the SPI-1 TTSS since a type III-deficient ΔinvA mutant did not cause observable pathology in this infection model system." (PMID 19662166, 2009). "At 5 h post-infection, the Lp type IV secretion system (T4SS) and the S.Tm SPI-1 T3SS were required for the early drop of the oxygen consumption rate." (PMID 41757918, 2026). "(H) FAO assay of uninfected (UI) and infected RAW 264.7 macrophages under infection with wildtype S. Typhimurium (STM WT), SPI-1 (∆invC), or SPI-2 (∆ssaV and ∆steE) mutants of S. Typhimurium." (PMID 39693143, 2024). "For example, SPI-1, SPI-2 and SPI-6 homologs related to infection, survival and replication ability were identified in strain SMEH." (PMID 39203510, 2024). "The host inflammatory pathways and bacterial virulence affected by SPI-1 and SPI-2 were also determined in macrophages and in a mouse infection model." (PMID 37325511, 2023). "We found that levels of TBX2, GATA3, RORC, SPI1, and BCL6 in the livers of infected rabbits were elevated on days 5 and 15 post-infection (PI)." (PMID 37593762, 2023). "We propose that elevated expression of motility-chemotaxis and SPI-1 genes, in conjunction with flagella-mediated motility, prime SPA toward a new cycle of host cell infection, supporting systemic dissemination of this pathogen in the human body." (PMID 35381053, 2022). "After infection, several additional pro-inflammatory upstream regulators including PTGS2 (COX2), IL1A, TNF, and SPI1 (PU.1) were activated at higher levels in aged mice." (PMID 35614490, 2022). "An initial and repetitive infection with a NTS T3SS mutant ΔprgH significantly reduced the transformative effect of an NTS infection, indicating that a functional SPI1 T3SS is involved during both initial and recurrent NTS-infection-induced transformations." (PMID 36543099, 2022). "RtsA induces expression of HilA, HilD, HilC, and InvF, all transcriptional factors of a complex regulatory network that activate SPI-1 genes and T3SS effectors required for the invasion stage of infection." (PMID 33803635, 2021).
infection (continued). "Given the changes to SPI-1 and SPI-2 gene expression detected in the OX strain, this strain and the GX and WT strains were compared in an in vitro infection assay using cultured HeLa cells." (PMID 32900812, 2020). "SPI-1 contains genes, which are essential for the early infection process to host cells, while SPI-2 contains genes that contribute to late infection processes of survival and replication inside host cells." (PMID 31195964, 2019). "There is significant crosstalk between regulators of the SPIs, and models with distinct roles for SPI-1 and SPI-2 in early and later stages of infection, respectively, are likely overly simplistic." (PMID 30682134, 2019). "The observation that there is a certain level of cross talk between the two secretion systems has led to an understanding that both SPI-1 and SPI-2 are important virulence factors during the process of infection (Moest and Méresse, 2013)." (PMID 31214517, 2019). "Both SPI-1 and SPI-2 contained two independent type three secretion systems (denoted as TTSS SPI-1 and TTSS SPI-2, respectively) that can inject effect or proteins into host cells, which are crucial for various stages of infection." (PMID 29755416, 2018). "In fact, the expression of SPI-1 and SPI-2 and repression of flagellar genes observed in the co-culture resembles the transcriptional profile of Salmonella cells in fibroblast after infection." (PMID 26988691, 2016). "During infection, SPI-4 acts in consort with SPI-1 to initiate invasion in to host epithelial cells." (PMID 25667583, 2015). "The consecutive expression pattern of SPI1 followed by SPI2 expression during transit through stationary phase mimics the infection situation whereby SPI1 largely precedes SPI2 expression and they rarely occur simultaneously in the same niche." (PMID 24664308, 2014). "We have found that SPI1 and SPI2 contribute to intraspecies colonization resistance up to 70 days post-infection." (PMID 25474319, 2014). "The human pathogen Salmonella uses two types of T3SS (SPI-1 and SPI-2) at different stages of host infection, while nitrogen-fixing Rhizobiales use a particular T3SS (Rhizobiales type) to establish symbiotic interactions with host plants." (PMID 25426102, 2014). "For effectors that can be secreted by either SPI-1 or SPI-2 T3SS, we observed decreased persistence for all mutant strains except ΔsseK1 at later times post-infection suggesting that they were essential for persistence in the host." (PMID 23950998, 2013). "Infiltration with SPI-1 T3SS mutants (prgH− and invA−) showed stronger symptoms from the first day onwards, if compared to infection with the wild type 14028s Salmonella." (PMID 22812426, 2012). "We observed that the SPI-1 T3SS in ΔmreC is completely down-regulated, and as this virulence system is important for infection through the oral route of inoculation the strain would be attenuated." (PMID 22291596, 2012). "S. Typhimurium 14028 s as well as the SPI-1 mutant were found to activate the MAP kinases at 15 and 30 minutes after infection (MAI) (43kDa and 42kDa bands), the signal decreases however at 60 MAI." (PMID 22812426, 2012). "Salmonella makes use of SPI-1 and SPI-2 T3SSs injecting several effectors with different functions at different stages of the infection." (PMID 22812426, 2012). "The SPI-1 T3SS effector protein SipB activates caspase-1, triggering programmed pro-inflammatory cell death (pyroptosis) within 45 minutes of infection." (PMID 20649986, 2010). "Both SPI-1 and SPI-2 T3SSs expressed by Salmonella are able to induce macrophage death, although by distinct mechanisms and at different times of infection." (PMID 20649986, 2010). "To assess the roles of SPI1 and SPI2 in the colonization of the gut and internal organs of the chicken, we used a mixed infection approach." (PMID 19126220, 2009).
infection (continued). "To gain better insight in the roles played by SPI1 and SPI2 in the chicken we used an approach that combined mixed infections, large deletions in SPI1 and SPI2, and the tracking of infections for fourteen days." (PMID 19126220, 2009). "The approach we used in this study constitutes a sensitive assay that provided new insights into the role of SPI1 and SPI2 during infection." (PMID 19126220, 2009). "Within the population of negatively selected mutants there was a significant overrepresentation of genes located in SPI-1 (36/395) and SPI-2 (51/395) indicating their importance in this infection model." (PMID 19649318, 2009). "Notably, H-NS binding in SPI-1, SPI-2, SPI-4, ybjX, and hns showed a significant increase before infection." (PMID 39868540, 2025). "Intraperitoneal infection bypasses the need for invasion, and SPI1 is not required for infection by this route." (PMID 40013798, 2025). "Furthermore, within the transcription factor-gene network, SPI1 is closely related to NCF4 and CEBPA, both of which have a role in macrophage activation and infection response." (PMID 40677917, 2025). "In competition experiments using CBA/J mice at ten days post-infection, the fraB80::kan mutant was attenuated 25-fold compared to wild-type, while a fraB80::kan SPI1 SPI2 triple mutant was not attenuated compared to a SPI1 SPI2 double mutant." (PMID 41474808, 2025). "Therefore, cell culture infection assays were performed on human-derived INT-407 and swine-derived IPEC-J2 intestinal epithelial cells to confirm the role of SPI-1 also in this serovar." (PMID 39660884, 2025). "Infection with S. Typhimurium T3SS mutants showed that macrophage LDH release is dependent on SPI2 (response regulator ΔssrB) but not SPI1 (secretion apparatus component ΔinvA)." (PMID 38497655, 2024). "Our findings indicate that the CRISPR-Cas system may influence the expression of virulence factors like antioxidant genes (sodA, sodCI, katG, and ahpC), SPI-1 and SPI-2 effectors, thereby playing a role in Salmonella’s virulence during host infection." (PMID 39462402, 2024). "As we were interested in components immediately relevant to infection and virulence, cells were harvested at OD600 of 1, when peak production of the SPI-1 transcriptional master regulator, HilA, occurs in Salmonella, and in the exponential growth phase for Listeria56,57." (PMID 38071303, 2023). "During infection with non-engineered WT S. Typhimurium, the bacteria naturally express both flagellin, SPI1 rod, and SPI1 needle in the gut lumen." (PMID 38055781, 2023). "Collectively, these results indicate that SPA expresses SPI-1 genes at higher levels during infection of non-phagocytic cells, in comparison to intracellular STM." (PMID 35381053, 2022). "At 1.5 h post infection, chloroquine‐resistant cytosolic SPtA 9150 were detected at low numbers, and bacterial escape into the cytosol was independent of SPI‐1 T3SS or the very long O‐antigen chains." (PMID 33355403, 2021). "Infection-induced cytokine gene expression was rapid, transient, and largely independent of SPI-1 T3SS-mediated invasion, likely due to continued luminal stimulation." (PMID 34006652, 2021). "When using the SPI-1 knock-down strain of S. Typhimurium, the infection number in BMDMs and LDH release were not changed by ASC knockout, and only a nonsignificant effect by SCFAs was observed in wild-type BMDMs." (PMID 32991574, 2020). "SPI-1 and SPI-2 harbor T3SS-1 and T3SS-2, respectively, and regulate expression of virulence genes including secretion of T3SS effector proteins in a highly regulated manner to establish infection in the host." (PMID 31195964, 2019). "This infection-dependent directional switch is independent of the Salmonella pathogenicity island 1 (SPI-1) type III secretion system." (PMID 30964858, 2019). "The presence in all Salmonella subspecies and clinical isolates indicates a critical and non-redundant function of SPI1 also during human infection." (PMID 29522566, 2018).